CD9 (CD9 molecule)
Diseases named in the same sentence as CD9 in open-access papers (continued):
Sharing a sentence is not in itself a finding about the gene and the disease.
prostate carcinoma (continued). "Using microarrays and luciferase assays in tumourigenic and non-tumourigenic prostate cell lines we identified miR-518f-5p as a regulator of the CD9 3'UTR gene expression, and decreased expression of endogenous CD9 in non-tumorigenic prostate RWPE1 and prostate cancer DU145 cells." (PMID 29416746, 2018).
gastric cancer (32 papers, 2002 to 2025). A primary or metastatic malignant neoplasm involving the stomach. "The observed differences in EV size and CD9 representation in gastric juice-derived vesicles can contribute to the development of new liquid diagnostic markers for gastric cancer." (PMID 40565320, 2025). "In line with our findings, it is of particular interest that CD9-positive EVs from cancer-associated fibroblasts stimulate the migration and invasion of scirrhous-type gastric cancer cells." (PMID 40565320, 2025). "The expression of CD9 is diminished in gastric cancer and has been proposed to be inversely associated with lymph node metastasis and with increased recurrence risk." (PMID 34576100, 2021). "We demonstrated that CD9 protein levels were inversely associated with lymph node metastasis of gastric carcinoma." (PMID 21521534, 2011). "Furthermore, the reduction of CD9 protein was associated with distant metastasis of gastric cancer." (PMID 21521534, 2011). "The expression of CD9 is higher in primary and metastatic gastric cancer tissues than in adjacent tissues of the same patient, and high expression of CD9 is associated with vascular invasion, lymph node metastasis, and advanced stage." (PMID 40860827, 2025). "In the case of gastric carcinoma, increased CD9 expression has been observed in primary tumors and metastatic lesions, and a correlation has been demonstrated with vessel invasion, lymph node metastasis, and advanced stage." (PMID 40565320, 2025). "In a xenograft model, the anti-CD9 antibody (ABL6) also inhibited the growth of human gastric cancer cells." (PMID 38389703, 2024). "For instance, miR-142-5p was up-regulated by LSD1-deleption and repressed cell migration via targeting CD9 in gastric cancer." (PMID 37403081, 2023). "Here, we focus on the insights into the roles and molecular mechanisms of three tetraspanins involved in gastric cancer cell metastasis, CD9, CD63, and CD82 (also known as KAI1)." (PMID 34222025, 2021). "CD9-positive exosomes from CAFs increase the migration abilities of scirrhous-type gastric cancer cells and the prognosis is worse in patients with positive CD9 in cancer cells." (PMID 34222025, 2021). "On the other hand, CAFs from scirrhous-type gastric cancer secretes exosomes CD81-negative/CD9-positive, which can promote cancer cell migration and invasion by activating the MMP2 signaling pathway." (PMID 33899109, 2021). "Animal experiments have shown that ALB6, a mAb targeting CD9, can significantly inhibit the progression of gastric cancer." (PMID 34222025, 2021). "We found that the gastric cancer cell-derived exosomes (GC-Ex) displayed sphere-like morphology with a diameter ~100 nm and expressed the exosomal markers CD9 and CD63." (PMID 30292233, 2018). "And in the future, we can also establish a gastric cancer cell model overexpressing CD9, CD63 or CD82, by using a plasmid vector." (PMID 21521534, 2011). "Recent studies comparing gastric cancer and normal tissue have identified a number of genetic markers, including diagnostic markers [NF2, INHBA, SFRP4], prognostic markers [CD9, CDH17, PDCD6], and gastric cancer-associated genes [MUC13, CLDN1, Ki67 and CD34]." (PMID 22133303, 2011). "Out of 49 gastric cancer tissues were studied by employing immunohistochemistry, 18 cases (36.7%) were classified as CD9 positive." (PMID 21521534, 2011). "Notably, the proportion of CD9-positive samples differed between healthy donors and gastric cancer patients." (PMID 40565320, 2025). "Their experiments revealed the unique role of CD9 in scirrhous-type gastric cancer." (PMID 34222025, 2021). "CD9 has an inhibitory effect on gastric cancer cell migration, and it plays a vital role in the development of gastric cancer, so CD9 may be a potential therapeutic target for gastric cancer." (PMID 34222025, 2021).
gastric cancer (continued). "In summary, CD9 maybe a powerful potential molecular target for gastric cancer therapy, but there is still a long way to go in improving the effectiveness of the treatment and overcoming the side effects." (PMID 34222025, 2021). "An in vivo study using administration of the CD9 antibody to mice bearing human gastric cancer xenografts showed inhibition of tumor progression via anti-proliferative, pro-apoptotic and anti-angiogenetic effects, suggesting its potential for the molecular-targeted therapy of human malignancies." (PMID 23128478, 2013). "The classification of gastric cancers according to CD9, CD63 and CD82 expression might be useful in identifying patients for whom intensive adjuvant therapy is warranted." (PMID 21521534, 2011). "This anti-CD9 mAb ALB6 could be used to treat gastric cancer for the following reasons." (PMID 34222025, 2021). "In summary, the dominant view is that CD9, CD63, CD82 are metastasis suppressors and are negatively correlated with gastric cancer progression and lymph node metastasis." (PMID 34222025, 2021). "CD9+ CAF-derived exosomes stimulate migration and invasion in scirrhous-type gastric cancer cells, and promote increased MMP-2 activity." (PMID 32957712, 2020). "Previously it was shown that decreased expressions of CD9 and CD82 were vital for colon cancer metastasis, and particularly reduced expression of CD82 was related with metastatic colon and gastric cancer." (PMID 30289336, 2019). "To further elucidate the decreased expression of eGPC3 in patients with gastric cancer, we sought to compare the expression of GPC3 and CD9 in total serum and corresponding isolated exosomes from five patients with GEA." (PMID 31100935, 2019). "The reduction of CD9, CD63 and CD82 expression are indicators for the metastatic potential of gastric carcinoma cells." (PMID 21521534, 2011). "The aim of this study was to clarify the clinical significance of TM4SF members CD9, CD63 and CD82 in human gastric carcinoma." (PMID 21521534, 2011). "Although cd9 has been studied to regulate the malignant progress of gastric cancer, its relationship with ITGB1 has not been reported in the literature." (PMID 34326374, 2021). "Chen’s lab found the expression level of CD9 and CD63 was decreased in gastric cancer." (PMID 34222025, 2021). "CAF-derived exosomes taken up by scirrhous-type of gastric cancer but not in the other types; CD9-positive CAF-derived exosomes promoted migration and invasion in scirrhous-type gastric cancer cells through MMP-2 activation." (PMID 32957712, 2020). "MKN-28, a human gastric cancer cell line is known to overexpress CD9, whereas HepG2, hepatocarcinoma cell line not to express CD9." (PMID 22989299, 2012). "Out of 49 gastric cancers tissues investigated, 17 carcinomas (34.7%) were evaluated as CD9 positive and 32 carcinomas (65.3%) as CD9 negative." (PMID 21521534, 2011). "Moreover, CD9 expression in gastric cancer is higher than non-cancerous tissues, thereby the adverse effects of anti-CD9 mAb therapy might be tolerable." (PMID 34222025, 2021).
glioma (29 papers, 2012 to 2025). A benign or malignant brain and spinal cord tumor that arises from glial cells (astrocytes, oligodendrocytes, ependymal cells). "In the multivariate Cox regression model, high CD9 expression was associated with a hazard ratio (HR) of 1.28 (95% confidence interval [CI]: 1.03–1.58), indicating that elevated CD9 expression serves as a significant risk factor for glioma (p < 0.026)." (PMID 40406701, 2025). "This study developed and validated a CD9-based prognostic model for glioma, with MR analyses confirming the causal relationship between CD9 and gliomagenesis and progression." (PMID 40406701, 2025). "CD9 is a prognostic biomarker in glioma, with causal evidence linking its overexpression to tumor development." (PMID 40406701, 2025). "By implementing MR analyses through the FinnGen dataset, we mitigated confounding biases inherent in observational measurements, thereby confirming the causal link between CD9 and glioma." (PMID 40406701, 2025). "Two-sample Mendelian randomization (MR) assessed the causal link between CD9 expression and glioma risk using IVW, MR-Egger, and WM methods." (PMID 40406701, 2025). "For genes linked to high CD9 expression, significant enrichment was observed in glioma-related pathways." (PMID 40406701, 2025). "Although this study primarily focuses on the prognostic value of CD9 in glioma, the exploration of its underlying mechanisms provides deeper insights into glioma biology." (PMID 40406701, 2025). "Our analysis of 1,033 glioma patients demonstrated a strong correlation between elevated CD9 expression and poor prognosis, with high CD9 expression associated with significantly shorter overall survival compared to low expression." (PMID 40406701, 2025). "Moreover, MR established the causal relationship between CD9 and glioma by integrating SNPs associated with CD9 and glioma GWAS data." (PMID 40406701, 2025). "Univariate and multivariate Cox regression analyses were performed to evaluate the impact of Radiotherapy, Chemotherapy, WHO grade, IDH status, MGMT methylation status, 1p19q codeletion status, age, gender, and CD9 expression on glioma prognosis." (PMID 40406701, 2025). "Mechanistic exploration of CD9’s role in GSC-TAM crosstalk and extracellular vesicle biology, alongside preclinical testing of CD9-targeted therapies, remains critical to advancing glioma therapeutics." (PMID 40406701, 2025). "While existing glioma prognostic models predominantly rely on clinicopathological features, our CD9-integrated model synergizes traditional and molecular biomarkers, achieving superior predictive accuracy." (PMID 40406701, 2025). "Single-cell analysis and PPI network exploration revealed the distribution patterns, dynamic expression trends, and interaction networks of CD9 across distinct glioma cell subpopulations." (PMID 40406701, 2025). "CD9 regulated glioma progression via calcium signaling and synaptic pathways, interacting with ITGB1 and CD81." (PMID 40406701, 2025). "This study evaluates the prognostic significance and functional mechanisms of tetraspanin CD9 in glioma to establish its clinical relevance and identify therapeutic strategies." (PMID 40406701, 2025). "The analysis further confirmed diverse phenotypic states within glioma stem-like cells, each defined by unique gene expression profiles, and underscored dynamic CD9 expression patterns across distinct biological differentiation processes in glioma." (PMID 40406701, 2025). "This study aims to establish CD9 as a prognostic biomarker for glioma through integrative multi-omics analysis, delineate its interaction networks driving tumor progression, and identify therapeutic agents targeting CD9-associated pathways." (PMID 40406701, 2025). "This positions CD9 as a pivotal prognostic biomarker in glioma, offering independent prognostic value beyond established factors such as age, WHO grade, IDH mutation, and 1p19q codeletion status in multivariate Cox analysis." (PMID 40406701, 2025).
glioma (continued). "Applying single-cell proteomic analysis and mass cytometry, their results have shown that CD9+/CD133+ glioma cells implanted in animal models have substantially lower survival than other glioma stem cell subtypes." (PMID 38448914, 2024). "It was proposed that the upregulation of CD9 expression at the onset of gliomagenesis (corresponding to low-grade glioma) facilitates the accumulation of radio-resistant stem cells." (PMID 39684236, 2024). "It is possible that the upregulation of CD9 expression early in the glioma genesis facilitates accumulation of radioresistant stem-like cells later on." (PMID 36203458, 2022). "We found that CD9 protein was visible uniformly across all three GSC lines, which will enable us to use CD9 antibody to uniformly capture and isolate all exosomes from glioma stem cells in future studies." (PMID 35269915, 2022). "The volcano plot revealed that glial cells in C5 derived from TDL upregulated expression of myelin-related genes (TYMP, CD9, MAG, and PMP22) and immune-related and inflammatory response-associated genes (IL1B and CXCL8) comparing to those from glioma." (PMID 36085357, 2022). "For example, in 2020 the research group led by Fabrício Figueiró demonstrated that glioma-derived extracellular vesicles expressing CD9, HSP70, CD39, and CD73, and producing adenosine, reduced glioma progression by modulating the tumor microenvironment." (PMID 33808435, 2021). "In a model of glioma, CD9-enriched EVs derived from endothelial cells also enhance glioma stem cell tumorigenesis by activating the BMX/STAT3 axis." (PMID 33738282, 2021). "GFAP positive CD9+ exosomes of total CD9+ exosomes were 7.9 times higher in patients with recurrent glioma (22.8%; 18.2–27.1%) compared to healthy controls (2.9%; 2.7–3.2%) at baseline." (PMID 30667110, 2019). "In contrast, survivin was present in 9.1% of CD9+ exosomes of glioma patients and only 0.43% of controls (a 21-fold difference)." (PMID 29383115, 2017). "Serum from glioma patients contained abundant CD9+ exosomes with both SVN and glial fibrillary acidic protein (GFAP) on their surface." (PMID 29383115, 2017). "In the glioma patients, a relatively large fraction (range 18.2 – 27.1%; mean = 22.8%) of CD9+ exosomes had GFAP on their surface." (PMID 29383115, 2017). "Taken as a single marker, survivin was present on an average of 9.1% of CD9+ exosomes of glioma patients (range 0.8 – 35%) at baseline (i.e. before vaccination) and on an average of 0.43% of control CD9+ exosomes (range 0.0 – 1.2%; a 21-fold difference)." (PMID 29383115, 2017). "The double marker GFAP+/SVN+ subpopulation of CD9+ exosomes was much higher in glioma patients (range 0.6 – 27.2%; mean = 6.8%) than in controls (range 0.0 – 0.1; mean = 0.03%), a 227-fold difference." (PMID 29383115, 2017). "We thus confirmed the contribution of CD9 to the malignancy of gliomas and GSCs, and propose to investigate CD9 further as a therapeutic target for GBM treatment." (PMID 26573230, 2016). "In a study revealing a model for identifying a cancer initiating cell, Liu and co-workers reported a high expression of CD9 leading to the proneural subtype of glioma." (PMID 26573230, 2016). "Different interactions between CD9 and other markers specific for oligodendrocyte precursor cells and the tumor niche components occur during development of different glioma subtypes." (PMID 26573230, 2016). "Gene expression analysis using the REMBRANDT database tool revealed increased CD9 expression in gliomas, including GBM, compared to normal brain." (PMID 26573230, 2016). "Collectively, this study systematically elucidates the central role of CD9 in glioma through prognostic modeling, molecular mechanism investigation, and therapeutic target prediction, providing a multifaceted framework for advancing glioma research and therapy." (PMID 40406701, 2025).
glioma (continued). "The highly dense intercellular connections within the PPI network suggest that CD9 may contribute to sustained enhancement of glioma cell proliferation signaling pathways." (PMID 40406701, 2025). "MR confirmed a causal association between CD9 and glioma risk (IVW OR = 1.33, p < 0.05) with no horizontal pleiotropy." (PMID 40406701, 2025). "The network comprises 20 nodes, revealing complex interactions between CD9 and other genes or proteins that may participate in glioma biology." (PMID 40406701, 2025). "Single-cell sequencing revealed enriched CD9 expression in neural progenitor-like (NPC-like) glioma stem cell subpopulations, with pseudotemporal trajectory analysis showing progressive downregulation during differentiation toward oligodendrocyte precursor-like (OPC-like) cells." (PMID 40406701, 2025). "The expression of the tetraspanin CD9, responsible for the maintenance of glioblastoma-like stem cells, and of CD81, associated with enhanced resistance to radiotherapy, is increased in low-grade gliomas and glioblastoma, respectively." (PMID 39684236, 2024). "Indeed, CD9+/CD133+ glioma cells have higher tumorigenic and temozolomide resistance than other subtypes." (PMID 38448914, 2024). "Overexpression of CD9 is also found in high-grade glioma, including the C6 glioma cell line." (PMID 37512530, 2023). "Moreover, in patients with glioblastoma, high CD81 expression correlated with shorter survival, while, in patients with low-grade glioma, high CD9 expression correlated with shorter survival." (PMID 36203458, 2022). "Previous studies have demonstrated that IL‐6 recruits gp130 by binding to its receptor, the membrane‐bound IL‐6 receptor (mIL‐6R), to activate STAT3.36, 37, 38 Moreover, CD9 stabilizes gp130 to activate STAT3 in glioma stem cells by preventing its ubiquitin‐dependent lysosomal degradation." (PMID 31837208, 2020). "The decreased proteins include proteins with known functions for glioma stemness and migration/invasion like CD9 (Gos, ATO/Gos), Ephrin receptor A2 (EPHA2; Gos, GANT/Gos) and mesenchymal (i.e., more aggressive) differentiation like FRAS1 related extracellular matrix protein 2 (FREM2; ATO/Gos)." (PMID 30871073, 2019). "Our proteomic data suggested the disturbance of processes related to cell movement, highlighted by decreased levels of several proteins involved in glioma migration, such as CD9 and EPHB3 after treatment with Gos or ATO/Gos, as well as EPHA2 after treatment with GANT/Gos." (PMID 30871073, 2019). "Moreover, in the CD9+/GFAP+ subpopulation, double-positive exosomes from glioma patients appeared as a much higher percentage of CD9+ exosomes (mean = 6.8%) than in controls (mean = 0.03%), a 227-fold difference." (PMID 29383115, 2017). "There have been conflicting reports on CD9 expression, and it has been shown to be either increased or decreased, possibly acting as a tumor suppressor in different cancer types including glioma." (PMID 26573230, 2016). "The survival queries revealed that for the 161 patients with glioma that showed > 2.0-fold up-regulation of CD9, there was a 50% shorter median survival, compared to the group of seven glioma patients with 2.0-fold down-regulation of CD9 (24 months vs. 48 months, respectively; p = 0.04)." (PMID 26573230, 2016). "Notably, functional loss of tetraspanin CD9 led to a marked increase in EGF-stimulated tumor cell invasion, consistent with recent analyses of CD81 and its associated EWI-2 protein complexes in gliomas." (PMID 26377974, 2015). "This adverse prognostic effect of elevated CD9 expression was consistently observed in both IDH-mutant and IDH-wildtype gliomas." (PMID 40406701, 2025). "Analyzing data accessible at the GEPIA platform, we detected increased expression of CD9 and CD81 in glioblastoma and low-grade glioma, proposing an upregulation of both tetraspanins early in the tumorigenesis of gliomas." (PMID 36203458, 2022).